CTLA4 (cytotoxic T-lymphocyte associated protein 4)
Diseases named in the same sentence as CTLA4 in open-access papers (continued):
Sharing a sentence is not in itself a finding about the gene and the disease.
melanoma (continued). "High dose IL-2 and CTLA-4 blockade have demonstrated clinical success in the treatment of advanced melanoma although the exact mechanism of their anti-tumor activity is not completely defined." (PMID 25992289, 2015). "We present a case involving the treatment of a patient with stage IV melanoma and ulcerative colitis (UC) with anti-CTLA-4 antibody immunotherapy." (PMID 25992290, 2015). "Immunotherapy against PD-1 and CTLA-4 targets two mechanisms that allow melanoma to evade immune attack—PD-L1 expression on melanoma cells to inactivate cytotoxic T-cells and CTLA-4 expression on lymphocytes which inhibits T-cell activation." (PMID 26426052, 2015). "In the interim, the data support clinical development of IL-2 and CTLA-4 blockade as a rational combination immunotherapy for patients with melanoma." (PMID 25992289, 2015). "Anti-CTLA-4 therapy has shown some efficacy in melanoma tumors and is being investigated in lung cancer." (PMID 29546098, 2015). "The approval of sipuleucel-T for the treatment of prostate cancer in 2010 and ipilimumab (anti-CTLA-4) for advanced melanoma in 2011 was the first notable success in the immunotherapy of cancer." (PMID 26137543, 2015). "Patients who died of melanoma during follow-up had a trend towards more circulating highly CTLA-4+ Tregs (P = 0.081)." (PMID 25592374, 2015). "Given this breakthrough success, the anti-CTLA-4 mAb was approved by FDA in 2011 for the treatment of patients with advanced melanoma." (PMID 26877890, 2015). "Ipilimumab is a fully human, monoclonal antibody directed against Cytotoxic T Lymphocyte Antigen-4 (CTLA-4) that has demonstrated a survival benefit and durable disease control in patients with advanced melanoma." (PMID 25317333, 2014). "Two phase 3 studies have demonstrated that the human CTLA-4 blocking antibody, ipilimumab, offers a benefit in overall survival for patients with advanced melanoma, leading to the FDA-approval of ipilimumab in March 2011." (PMID 25642417, 2014). "We have preliminary data that suggest that in mouse models, aging diminishes both the effect of CTLA-4 on the growth of B16 melanoma and the ability of an anthracyclin-based tumor vaccine to produce protective anti-tumor immunity (data not shown)." (PMID 24682539, 2014). "A case study shows exacerbation of sarcoidosis in a melanoma patient treated with anti-CTLA-4 monoclonal antibody inhibitor ipilimumab." (PMID 25191698, 2014). "With the clinical success of monoclonal antibodies against inhibitory immune checkpoint proteins in melanoma, including CTLA-4 and PD-1, anti-MMP-23 therapy also holds promise as a potential treatment strategy." (PMID 25491880, 2014). "Combining CTLA-4 blockade and 4-1BB co-stimulation with a granulocyte-macrophage colony-stimulating factor (GM-CSF)–secreting melanoma vaccine greatly improved tumor eradication and promoted survival compared with vaccine plus either agent." (PMID 24855562, 2014). "Th17 cell induction has already been described with various melanoma treatments, such as vaccination, anti-PD-1, anti-CTLA4, as well as other anticancer drugs such as cyclophosphamide." (PMID 25170840, 2014). "While hypothyroidism is 5–6× more prevalent in females in Caucasians, thus far hypophysitis from anti-CTLA-4 therapy has occurred mostly in males, in part influenced by the ratio of female:male of ~1:2 in melanoma patients." (PMID 24904570, 2014). "The FDA-approval of the CTLA-4 blocking antibody, ipilimumab (Bristol-Myers Squibb), and the PD-1 blocking antibody, pembrolizumab (Merck) in the treatment of advanced melanoma appear to represent the proverbial tip of the iceberg." (PMID 25642417, 2014). "Monoclonal antibodies targeting CTLA4, such as ipilimumab, should be evaluated in myeloma as they have been, for example, in melanoma." (PMID 25099367, 2014). "Pruitt and colleagues saw improvements in antitumor immunity when a melanoma DC vaccine was combined with DCs expressing anti–CTLA-4 and anti-GITR mRNA." (PMID 24855562, 2014).
melanoma (continued). "Phase I clinical trial development of the anti-CTLA-4 + anti-PD-1 combination has already been pursued in advanced melanoma, with profound clinical response rates observed that appear superior to single agent activity based on historical controls." (PMID 24829760, 2014). "Baseline (pre-treatment) serum CRP was reported to have a potential therapeutic predictive value in melanoma patients treated with the anti-CTLA4 antibody tremelimumab." (PMID 24457057, 2014). "Antibodies that block the co-inhibitory T-cell molecules CTLA-4 and PD-1 plus GM-CSF have boosted immune responses against melanomas." (PMID 24971166, 2014). "Here, RRP10 reference pattern is the common context in all these CTLA-4 genotype relationship patterns, which are significantly biased between the longer and shorter surviving melanoma patients." (PMID 24475110, 2014). "While several groups are currently working on this approach, published studies to date have focused on ipilimumab, an anti-CTLA-4 antibody approved to treat melanoma in 2011." (PMID 25101247, 2014). "When humanized CTLA-4 mAbs were first used to treat advanced melanoma a decade ago, the major goal was to interfere with the negative signaling of an ongoing anti-tumor response discernible in many patients." (PMID 24904570, 2014). "Ipilimumab, a monoclonal antibody against cytotoxic T-lymphocyte antigen 4 (CTLA4), is one of the first treatments to provide beneficial durable responses in advanced melanoma." (PMID 24904825, 2014). "An important study has shown that combining blockade of both immune checkpoints (PD-1 and CTLA4) is highly synergistic in rejection of melanoma tumors in an animal model through strong stimulation of effector T cells and IFN-g production." (PMID 24743024, 2014). "Melanoma: Ipilimumab, an antibody against CTLA-4, was the first agent to improve median overall survival (OS) in patients with advanced melanoma." (PMID 26328216, 2014). "Toxicities from BRAF inhibitors or anti-CTLA-4 antibodies for melanoma, albeit low grade, are continuous and chronically impact on quality of life." (PMID 25053129, 2014). "Cytotoxic T-lymphocyte antigen 4 (CTLA4) ligation is important for the immunosuppressive function of regulatory T cells and anti-CTLA4 antibodies produced encouraging results in melanoma patients." (PMID 24885819, 2014). "The concept was recently examined in a phase I clinical trial, administering nivolumab (IgG4 antibody to PD-1) and ipilimumab (IgG1 antibody to CTLA4) in patients with stage III or IV melanoma." (PMID 24969320, 2014). "In murine pre-clinical models, GVAX combined with anti-CTLA-4 treatment enhanced efficacy and tumor regression in the B16 melanoma model, along with the presence of certain toxicities, such as skin depigmentation." (PMID 24782858, 2014). "We have previously demonstrated that CTLA-4 engagement with its natural ligands can deliver an apoptotic signal in haematological and solid tumor cells including melanoma cell lines." (PMID 23634660, 2013). "Ipilimumab is a fully human monoclonal antibody that binds and blocks CTLA-4 to sustain T cell activity, and it has been shown to improve overall survival of patients with advanced melanoma." (PMID 24326015, 2013). "Along these lines, additive effects have been observed for combined CTLA-4/PD-1 blockade in a B16 mouse melanoma model." (PMID 23533456, 2013). "Two central and well-studied immune checkpoints are theco-inhibitory receptors CTLA4 and PD-1; antagonists to both are currently in clinicaltrials for melanoma and other cancers." (PMID 24004819, 2013). "All melanoma cell lines expressed mRNA and cytoplasmic CTLA-4 but surface reactivity with Ipilimumab was quite heterogeneous." (PMID 23634660, 2013). "This ADCC led to efficient killing of several melanoma cell lines and it appears that the degree of this process was directly related to the level of CTLA-4 surface expression." (PMID 23634660, 2013).
melanoma (continued). "Recent phase 3 clinical trial with ipilimumab blockade of CTLA-4 has shown some clinical benefits in stage III/IV melanoma patients, suggesting the potential of suppressor cell inhibition in promoting endogenous anti-tumor immune responses." (PMID 23533812, 2013). "CTLA-4 expression in primary melanoma cell lines appeared to be independent from the stage of melanoma differentiation." (PMID 23634660, 2013). "Several clinical trials are now underway to evaluate safety and efficacy of combined PD-1 and CTLA-4 blockade in patients with renal cell carcinoma, non-small cell lung cancer, or melanoma (NCT01783938, NCT01472081, NCT01454102, NCT01024231)." (PMID 24353898, 2013). "CTLA-4 expression and Ipilimumab reactivity were analyzed on 17 melanoma cell lines (14 primary and 3 long-term cell lines) by cytofluorimetry and on 33 melanoma tissues by immunohistochemistry." (PMID 23634660, 2013). "Blockade of CTLA-4 with antibody led to tumor regression in 10-15% patients with advanced melanoma whereas severe autoimmune toxicity was evident in >30% of patients." (PMID 24326015, 2013). "For advanced melanoma, it is worth mentioning that administration of humanized anti-CTLA-4, ipilimumab improved survival of patients with metastatic melanoma in a clinical trial." (PMID 23874336, 2013). "This strongly suggests that the absence of the tumor microenvironment favours the in vitro selection of CTLA-4 positive melanoma cells." (PMID 23634660, 2013). "In the present study, we analyzed CTLA-4 expression in 14 primary cell lines originating from metastatic lesions of cutaneous melanoma patients and in 3 long-term established melanoma cell lines." (PMID 23634660, 2013). "Among these, immune checkpoint inhibition is most advanced in melanoma patients and anti-CTLA4 blockade was actually the first therapy that improved survival of patients suffering from metastatic melanoma." (PMID 24427158, 2013). "Ipilimumab triggered, via FcγReceptorIIIA (CD16), ex vivo NK cells as well as PBMC, IL-2 activated NK and γδT cells to ADCC of CTLA-4+ melanoma cells." (PMID 23634660, 2013). "Combination of CTLA4 and PD-1 blockade with anti-PD-1:B7-H1 monoclonal antibodies increases effector T-cell infiltration into B16 melanoma in mice, resulting in an elevated effector to Treg cell ratio within the tumor." (PMID 23861693, 2013). "Over the last 4 years, the advent of targeted therapy for BRAF mutated melanoma and immune checkpoint inhibitors, e.g. anti-CTLA-4, anti-PD-1, and anti-PD-1 L antibodies have sparked resurgence of excitement for the treatment of advanced stage melanoma." (PMID 24499550, 2013). "Herein, we show that patient-derived melanoma cells and tissues constitutively express CTLA-4 molecule." (PMID 23634660, 2013). "Ipilimumab reacts with CTLA-4 on melanoma cell lines and tissues and is able to trigger antibody dependent cellular cytotoxicity (ADCC) engaging FcγRIIIA on lymphocyte subsets such as primary NK cells, IL-2 activated NK and γδT cells." (PMID 23634660, 2013). "Our data show mRNA and cytoplasmic CTLA-4 expression in all primary melanoma cell lines tested, although the surface CTLA-4 expression was quite heterogeneous (MRFI ranging from 1.2 to 6.9), regardless their stage of differentiation and stemness phenotype." (PMID 23634660, 2013). "Here, CTLA-4/PD-1 blockade led, among others, to increased infiltration and cytotoxicity of melanoma-specific CD8+ T cells into the tumors." (PMID 23533456, 2013). "Both polyclonal and Ipilimumab anti-CTLA-4 antibodies reacted with the established human melanoma cell lines C32 and MeWo." (PMID 23634660, 2013). "Two randomized phase III trials showed a modest, but significant, response of melanoma to CTLA-4 antagonist ipilimumab." (PMID 23554566, 2013). "Herein, we have analyzed CTLA-4 expression and Ipilimumab reactivity on melanoma cell lines and tumor tissues from cutaneous melanoma patients." (PMID 23634660, 2013).
melanoma (continued). "We had previously reported CTLA-4 constitutive expression on established cell lines derived from different solid tumors, including melanoma." (PMID 23634660, 2013). "We demonstrate that CTLA-4 engagement with Ipilimumab triggers innate immune cells to ADCC of CTLA-4+ melanoma cells and Tumor Necrosis Factor (TNF)-α production." (PMID 23634660, 2013). "The combination of anti-PD-1 and anti-CTLA-4 was tested in murine B16 melanoma model and found to be more effective in tumor regression as compared to each of the blocking antibodies alone." (PMID 22778766, 2012). "Noteworthy, it was reported that CTLA-4 is also expressed by various tumor cells and in a Wnt-dependent manner in melanoma." (PMID 22778766, 2012). "Anti-CTLA-4 antibody therapy represents the start of a new era in the treatment of advanced melanoma but we are on the steep slope of the learning curve toward the optimization of their utilization either a single agents or in combination." (PMID 22077981, 2011). "Antibodies which block CTLA-4 or which activate 4-1BB can promote the rejection of some murine tumors, but fail to cure poorly immunogenic tumors like B16 melanoma as single agents." (PMID 21559358, 2011). "Recently, two studies using ipilimumab, an anti-CTLA-4 monoclonal antibody (mab) demonstrated improvements in overall survival in the treatment of advanced melanoma." (PMID 22077981, 2011). "CTLA-4+ TIL isolated from melanoma that also expressed Programmed Death-1 (PD1) produced very low levels of IFN-γ upon stimulation with PMA-Ionomycin, a strong non-specific stimulus." (PMID 24212939, 2011). "Taken with our data showing strong cooperativity between these agents in rejecting B16-BL6 melanoma, further studies are certainly warranted to assess the safety of using 4-1BB agonist antibody and CTLA-4 blockade in combination." (PMID 21559358, 2011). "TIL were shown by flow cytometry to express CTLA-4 in Hodgkin disease, melanoma and ovarian carcinoma." (PMID 24212939, 2011). "The early results using immunomodulator molecules have been encouraging (as an example CTLA4 blockade in melanoma patients) and one trial in melanomas recently demonstrated the potential interest of combination of CTLA4 blockade with a DC vaccine." (PMID 20953324, 2010). "Subsequently, anti-CTLA-4 antibodies have shown encouraging results in clinical trials in advanced melanoma." (PMID 24281101, 2010). "CTLA4 blocking monoclonal antibodies induce durable objective responses in some patients with melanoma mediated by T cell infiltrates in tumors, attesting to the immune nature of their benefit." (PMID 20875102, 2010). "In conclusion, this report of patients with advanced melanoma treated at MSKCC in a trial of compassionate use ipilimumab is consistent with other phase 2 evaluations of anti–CTLA-4 antibodies." (PMID 20143434, 2010). "Molecular targeted agents that inhibit the proliferation and survival of metastatic melanoma cells offer potential partners for anti-CTLA-4 antibodies in combined modality regimens." (PMID 24281101, 2010). "Increased Th17 cells have been reported in the blood of melanoma patients with autoimmune toxicities to the anti-CTLA4 antibody tremelimumab." (PMID 24281094, 2010). "Blockade of the inhibitory receptor CTLA-4 by mAbs has been tested as a single agent or in combinations in patients with advanced cancer, including breast cancer, lymphoma, melanoma, ovarian cancer, prostate cancer, and ccRCC." (PMID 21127709, 2010). "Early published reports of clinical trials of humanized anti-CTLA4 monoclonal antibodies have indicated a 10–20% partial response rate in melanoma patients." (PMID 18334033, 2008). "Administration of CTLA4-blocking antibody tremelimumab to patients with advanced melanoma results in a subset of patients with long-lived tumor responses." (PMID 18452610, 2008).
melanoma (continued). "Second, there was heterogeneity in prior treatments for these patients, and all participants had melanoma, and thus it remains unclear whether these genetic signatures will generalize to other cancer types treated with anti-CTLA-4 therapy." (PMID 40721801, 2025). "However, with the development of targeted therapies (such as BRAF, MEK, CDK4/6, and C-KIT inhibitors) and immunotherapies (including anti-CTLA4 antibodies and anti-PD-1 antibodies), the systemic treatment of melanoma has been dramatically revolutionized." (PMID 40641936, 2025). "Immune checkpoint inhibitors (ICIs), such as those targeting Programmed death ligand-1 (PD-1), Programmed death ligand (PD-L1), and Cytotoxic T lymphocyte-associated protein 4 (CTLA–4), have been approved for the treatment of various cancer types, including melanoma, lung cancer, and HNSCC." (PMID 40556669, 2025). "Indeed, we observed an accumulation of FoxP3+ iNKTreg cells within melanoma tumors, a disturbed NCR/NKG2 profile, and a skewed ICP expression toward LAG3, CTLA4, and TIM3, which were associated with early relapse and shorter survival." (PMID 41562072, 2025). "Some limitations of the study include its limited scope, as most patients were treated with melanoma, and all CTLA-4-treated patients were treated with ipilimumab, raising questions about whether this truly is a class effect." (PMID 40563660, 2025). "The role of NR2F1 in modulating immunotherapy responses also warrants investigation, including whether NR2F1-high melanomas are more responsive to PD-1 or CTLA-4 blockade, or if NR2F1 influences T cell infiltration." (PMID 40955667, 2025). "Additionally, the combination of genomic data and immune cell analysis has been shown to identify melanoma patients more likely to benefit from combination PD-1 and CTLA-4 inhibitor therapy." (PMID 41269529, 2025). "In addition to PD-1/PD-L1 blockade, CTLA-4 inhibition is being explored, with the anti-CTLA-4 monoclonal antibody ipilimumab, which shows promise in the treatment of melanoma brain metastases." (PMID 40628732, 2025). "Combining anti-PD-1 and CTLA-4 inhibition, primarily by partnering ipilimumab with nivolumab, has been approved for several of indications, including advanced non-small cell lung cancer, melanoma, and kidney cancer." (PMID 40606990, 2025). "Therefore, the aim of this study was to evaluate contrast-enhanced ultrasound (CEUS) with VEGFR2-targeted microbubbles for monitoring the effects of combined anti-PD-L1/anti-CTLA-4 immunotherapy in a murine melanoma model." (PMID 40591551, 2025). "This study assesses trends in incidence of neurologic irAEs in melanoma patients undergoing PD-1 inhibitor monotherapy compared to those receiving both anti-PD-1 and anti-CTLA-4 immunotherapies over time, unveiling insight into the relative risks associated with these treatment regimens." (PMID 40351833, 2025). "Combining VISTA inhibitors with anti–CTLA-4 or anti–PD-1 antibodies overcomes adaptive resistance mechanisms and leads to robust tumor regression in murine melanoma models by reducing Treg frequencies and increasing granzyme B+ cytotoxic T lymphocytes in the tumor." (PMID 40821795, 2025). "In melanoma treatment, integrating multi-omics has enhanced the clinical efficacy of immune checkpoint inhibitors (ICIs), such as PD-1 inhibitors (nivolumab, pembrolizumab) and CTLA-4 inhibitors (ipilimumab)." (PMID 41269529, 2025). "Checkpoint immunotherapy itself can also promote controlled translocation: anti-PD-1/anti-CTLA-4 regimens in mice induced movement of endogenous gut bacteria to tumor-draining lymph nodes and subcutaneous melanomas, where microbial sensing augmented antitumor T-cell responses." (PMID 41339918, 2025). "In turn, the primary response to anti-CTLA-4 therapy requires robust melanoma MHCI expression." (PMID 40108693, 2025).